EWSR1 (EWS RNA binding protein 1)
Diseases named in the same sentence as EWSR1 in open-access papers (continued):
Sharing a sentence is not in itself a finding about the gene and the disease.
tumor (continued). "The tumour cells expressed CD99 and molecular genetic investigations confirmed an EWSR1 rearrangement." (PMID 23379545, 2013). "The fusion transcript EWSR1/FLI1, as well as many other chimeric proteins, interferes with several molecular pathways, influencing the development and progression of this tumor." (PMID 23329308, 2013). "At the protein level a fusion of the amino-terminal domain (NTD) of the EWSR1 gene and three of the four carboxyl-terminal zinc fingers of the WT1 tumour suppressor gene takes place." (PMID 22587803, 2012). "Next-generation sequencing (NGS) analysis revealed copy number loss of SMARCB1 and a novel GSTT1::IGLC7 fusion in the tumor, while no other gene rearrangements, including those involving EWSR1, NR4A3, or FUS, were detected." (PMID 42052495, 2026). "EWSR1::FLI1 is essential for ES cell survival and tumor growth in mice." (PMID 39894896, 2025). "EWSR1::ETS enforces tumor identity through non-canonical, microsatellite-rich SEs, with minimal reciprocal regulation by MTFs." (PMID 41444391, 2025). "Differences in molecular fusion type (EWSR1/CREB1 versus EWSR1/ATF1), tumour burden at relapse, and prior treatments may partly explain the variability in responses across cases." (PMID 41020828, 2025). "All 13 DSRCTs harboured the EWSR1::WT1 oncogenic fusion and the unsupervised analyses on the expression profiles revealed the 13 cases as a specific and biologically homogeneous cluster among the other tumours." (PMID 39921935, 2025). "Currently, no standard treatment exists for neoplasms with EWSR1::CREB fusions, while complete surgical resection with negative margins is recommended as the main treatment strategy for these genetically defined tumor types." (PMID 41341384, 2025). "Concomitant detection of the EWSR1/ERG gene rearrangement in a patient with type II PPB has not been described so far in this type of tumor." (PMID 40868080, 2025). "Furthermore, 10 of these 26 (38.5%) patients had a tumor with an EWSR1::ATF1 fusion, eight (30.8%) had EWSR1::CREB1 fusion, six (23.1%) had EWSR1::CREM, one (3.8%) had EWSR1::CREB3L3, and one (3.8%) had FUS::CREM fusion." (PMID 38291529, 2024). "Undifferentiated small round-cell sarcomas (USRCSs) with EWSR1 fused to non-ETS gene partners were formerly considered as neoplasms related to the Ewing family of tumors but are now recognized as distinct entities." (PMID 38339014, 2024). "Given the lethality of EWSR1::ATF1 in multiple lineages, it may be worthwhile to investigate methods to promote oncogene-induced senescence and drive the tumor into an unstable and apoptotic state." (PMID 38916046, 2024). "Activating Myc resulted in more rapid Ewsr1::Atf1 tumor development, although these tumors did not histologically recapitulate CCS." (PMID 38916046, 2024). "This domain configuration fueled the idea that EWSR1::ATF1 chimeras act like aberrant transcription factors, which dysregulate the gene expression pattern of host cells, leading to unleashed proliferation and, thus, tumor formation." (PMID 39769457, 2024). "Specifically, 8 tumors harbored an EWSR1::CREM and one tumor a FUS::CREM in-frame fusion." (PMID 39249507, 2024). "One potential alternative explanation is that androgen is necessary for the formation of the EWSR1::WT1 fusion but not subsequent tumor growth." (PMID 38575753, 2024). "Besides EOR, age, and EWSR1::ATF1 fusion, we further identified another novel prognostic factor: tumor location." (PMID 38291529, 2024). "The tumor with EWSR1::RORB fusion showed a morphologic appearance that was not distinctive of any specific type of round-cell sarcoma." (PMID 38339014, 2024). "EWSR1::FLI1 repressed miR-708 expression to indirectly induce EYA3 transcription, and inhibited expression of the tumor suppressive miR-145, and other miRNAs including miR-22, miR29a, miR-100, miR-125b, miR-221/222 and miR-271 to modulate tumor growth." (PMID 36672331, 2023).
tumor (continued). "Similarly to EWSR1::FLI1, HIF-1-a expression has been shown to be heterogenous across EwS tumors and possibly also within a given EwS tumor." (PMID 36915100, 2023). "Notably, the EWSR-1-translocated case possessing morphologic subtype that was BSS exhibited an ambiguous transition between epithelial and spindle tumor cells, which was different from other BSS cases." (PMID 37193761, 2023). "Tumor specimens negative for EWS-specific fusion gene should be analyzed for the panel of known fusion transcripts including CIC-rearrangement, BCOR-rearrangement, EWSR1, or FUS fusion with no-ETS partner." (PMID 36358827, 2022). "Conversely, FISH assays utilize ‘break-apart’ probes that only identify a breakpoint in one of the common genes (e.g., EWSR1 present in different tumours) without providing information on the translocation partner." (PMID 36614077, 2022). "In the case of AF0052, the tumor recurred; the histological findings for the recurrent tumor were the same as those for the initial surgical specimen, but the samples were negative for EWSR1 and SYT in FISH analysis." (PMID 36033527, 2022). "Although multiple studies reveal various signaling pathways mediated by the EWSR1/FLI1 fusion, the specific transcriptional control of tumor cell resistance to doxorubicin is unknown." (PMID 36428591, 2022). "(C) Relative mRNA expression of human EWSR1-FLI and zebrafish nr0b1 in normal and tumor tissues." (PMID 35285802, 2022). "The analysis did not detect MDM2 amplification, Rb1 deletion, break apart signals of EWSR1, FUS, DDIT3, or c-myc, or c-myc-IGH fusion signals, but it did detect more c-myc signals in 837 out of 996 tumor cells and 823 out of 1,000 tumor cells." (PMID 36514176, 2022). "FISH analysis of fresh-tissue touch preparations detected EWSR1 split signals in most tumor cells but not FUS split signals." (PMID 34749732, 2021). "Furthermore, these cells retain the EWSR1-ETS fusion transcript and cell surface expression of CD99 with the tumours from which they were derived." (PMID 34403115, 2021). "Notably, circ‐CUX1 bound to RRM region of EWSR1, resulting in EWSR1‐mediated MAZ transactivation, suggesting the oncogenic roles of circ‐CUX1/EWSR1/MAZ axis in aerobic glycolysis and tumor progression." (PMID 31709724, 2019). "Due to lack of DNA‐binding domain, EWSR1 usually acts as a potent transcriptional cofactor in tumor progression via interacting with transcription regulatory proteins, such as CREB‐binding protein and p300." (PMID 31709724, 2019). "Case 13, which had both EWSR1 and CREM rearrangements (metastatic lesions in lymph nodes), showed sheet-like and fascicular proliferation of epithelioid and spindle tumor cells that had round nuclei with conspicuous nucleoli and abundant pale eosinophilic cytoplasm; no myxoid change was found." (PMID 30219084, 2018). "Histologically these showed a wide spectrum of architectures and cell types, including spindle, round and ovoid cells, and none of these fitted clearly into any particular group of EWSR1-rearranged neoplasms." (PMID 28141799, 2017). "RT-PCR with all four primer combinations—EWSR1-879F/PBX3-1198R1, EWSR1-986F/PBX3-1032R1, EWSR1-879F/PBX3-1032R1, and EWSR1-986F/PBX3-1198R1—amplified cDNA fragments strongly suggesting the presence of an EWSR1-PBX3 fusion transcript in the examined tumor." (PMID 25875009, 2015). "GNETs also exhibit EWSR1 gene rearrangements, confirming that this is not a tumor-specific characteristic." (PMID 25364450, 2014). "However, combined HHT treatment and EWSR1 depletion did not further reduce tumor growth compared to either intervention alone, suggesting that EWSR1 is required for HHT efficacy." (PMID 41472850, 2025). "In addition to the common EWSR1::WT1 fusion, DSRCTs commonly display alterations in other pathways that make the tumor more aggressive and allow it to spread early in its development, prompting tumor metastasis." (PMID 39682287, 2024).
tumor (continued). "Similarly, EWSR1::YY1-rearranged EM all clustered together and stood out from the other neoplasms." (PMID 39059063, 2024). "The comprehensive list of target tumor-driver genes of EWSR1::ATF1 is not known." (PMID 39769457, 2024). "Given this problem, it seems prudent to consider the combination of inhibitors against EWSR1/FLI1 or EWSR1/ERG with additional targeted therapies that might overcome tumor cells’ resistance to the monotherapy and might demonstrate a less adverse effect due to dose reduction." (PMID 35454895, 2022). "Instead, MRD detection in these cancers has focussed on the detection of tumour-specific messenger RNA (mRNA) using qRT-PCR of NB-specific RNA markers, such as TH and PHOX2B, or EWSR1 gene fusion transcripts with the ETS family or FLI1 gene for EWS-specific markers." (PMID 34471258, 2022). "Further investigations of cells that thrive without EWSR1 may reveal which critical functions must be restored for EWS-FLI1 to continue to sustain tumor growth and help identify new factors involved." (PMID 34035145, 2021). "Of note, this initially EWSR1 rearrangement negative case was positive for keratin (diffuse) and synaptophysin, however it is also noteworthy that this patient was an 11-year-old boy with a femur tumor." (PMID 34698236, 2021). "These probes show rearrangements in most other neoplasms with EWSR1 gene fusion and could not determine the genes that are fused with EWSR1." (PMID 34193155, 2021). "Molecular testing performed and interpreted at University of Nebraska, Omaha NE reported the tumor as negative for fusion of the EWSR1 (22q12) and ATF1 (12q13) loci, negative for rearrangement of the TFE3 (Xp11) locus, and negative for fusion of the EWSR1 (22q12) and CREB1 (2q33.3) loci." (PMID 30314519, 2018). "Interestingly, these pleomorphic tumor cells harbored an increased (up to 12 copies) number of rearranged EWSR1 genes in contrast to a signal copy in non-pleomorphic areas." (PMID 28114920, 2017). "The EWSR1-ETS upregulated proteins EZH2 and CHM1 were successfully used to prime allo-restricted T-cells but these are proteins expressed in many other tissues and could have serious side effects and lead to non-tumor specific targeting." (PMID 26193259, 2015). "Moreover, the Tumor (T) staging (P = 0.004), Nodule (N) staging (P = 0.008), and Tumor-Nodule-Metastasis (TNM) staging (P = 0.001), was well as AFP (P < 0.001) and Ki67 (P < 0.001) expression rates, and mortality (P < 0.001) were markedly higher in the EWSR1 overexpression group." (PMID 34612781, 2021). "It is unclear whether any of these neoplasms could represent specific, as yet uncharacterised tumour types harbouring EWSR1 rearrangements with unknown partner genes, or if these EWSR1 rearrangements might be non-reproducible and a function of the intrinsic genetic instability of the tumours." (PMID 28141799, 2017). "Subsequently, at a pathology consultation, the tumor was found to be negative for MUC4 and SSX (C-term), while FISH analysis detected rearrangements for both EWSR1 and CREM genes." (PMID 40242428, 2025). "Two patients with EWSR1::ATF1 fusion experienced recurrence or metastasis during the follow-up period, of which one died of the tumor, and two had no recurrence or metastasis during the follow-up period." (PMID 41341384, 2025). "Although we defined 260 and 49 EWSR1::FLI1-KDM6A and KDM6B direct targets, respectively, affecting oncogene reprogramming, the contribution of the two demethylases to tumor growth in an oncogene-independent manner should not be dismissed." (PMID 41085408, 2025). "A FISH study of intraosseous tumor dabs revealed CBFA2T3::GLIS2 fusion formation and the absence of EWSR1 rearrangement." (PMID 40565358, 2025).
tumor (continued). "Similarly, the absence of codons 65 to 109 of ATF1 in some EWSR1::ATF1 fusion products, apparently, excludes the putative activation domain of ATF1, raising the question of if the differential activity and, consequently, tumor specificity of these variants correlates to the tumor phenotype." (PMID 39769457, 2024). "Ewing-like SRCT comprises tumor with EWSR1 rearrangements with a non-ETS family partner and tumor with non-EWSR1-ETS rearrangements." (PMID 38427070, 2024). "In Case 1, the NUTM1 break-apart signal was observed in 84% of tumor cells, whereas the tumor was negative for BRD4::NUTM1, SS18, and EWSR1 rearrangements." (PMID 38239638, 2023). "The fluorescence in situ hybridization (FISH) test of the tumor tissue showed no broken rearrangement of the GLI1 gene and that of the EWSR1 gene in the patient’s tumor." (PMID 37658451, 2023). "Because EWSR1 fusions are identified in a diverse array of tumor types, FISH for EWSR1 is not specific for EWS; nonetheless, in the appropriate context, demonstration of EWSR1 rearrangement is sufficient to confirm the diagnosis." (PMID 36983010, 2023). "FISH studies demonstrated that the tumor was negative for amplification of MDM2 and rearrangements of EWSR1, FUS, and KMT2A." (PMID 34592995, 2021). "Respondents were mostly unsure of how to classify FUS-ETS gene family fusions and EWSR1 round cell sarcoma with non-ETS partners, which is consistent with their difficulty classifying these tumours and explained by their rare presentation." (PMID 33488267, 2020). "Genetic testing revealed no mutation in the Dicer 1, Ribonuclease III (DICER) gene, no translocation of the Ewing Sarcoma breakpoint region 1/EWS RNA binding protein 1 (EWSR1) gene, and no amplification of the Murine Double Minute 2 (MDM2) gene in the tumor cells." (PMID 40242239, 2025). "Therapeutic selection was guided by molecular profiling and tumour characteristics, particularly the NGS results from liver and peritoneal metastases, which revealed: PD-L1 expression of 15%, presence of the EWSR1/CREB1 fusion, no other actionable oncogenic drivers, and a Ki-67 index of 30%." (PMID 41020828, 2025). "With FISH analysis the tumor was FOXO1 and EWSR1 break negative." (PMID 35856126, 2023). "The breakpoint of EWSR1-ETS is not conserved and varies in every individual tumor/patient." (PMID 36046479, 2022). "However, EWSR1 and FUS rearrangements were absent in this tumor." (PMID 31915021, 2020).
cancer (208 papers, 2003 to 2026). A tumor composed of atypical neoplastic, often pleomorphic cells that invade other tissues. "The clinical evidence suggests a strong association between elevated levels of EWSR1 gene expression and decreased patient survival rates as well as unfavorable prognoses, highlighting EWSR1 as a potential target for cancer treatment." (PMID 41472850, 2025). "In stem/TA-like cells (cancer cells), there was a clear preference for EWSR1-207, which encodes a protein critical for preventing hematopoietic stem cell senescence, rather than EWSR1-216." (PMID 40702779, 2025). "For example, in Ewing sarcoma and osteosarcoma, the detection of ctDNA as indicated by cancer specific translocations like EWSR1, was associated with more advanced stage of cancer and poorer overall survival." (PMID 38310289, 2024). "The confirmation of EWSR1 gene rearrangement through FISH analysis further contributes to the diagnostic precision of this unique carcinoma." (PMID 38884096, 2024). "Decades later, a screen of hundreds of cancer cell lines seeking to identify biomarkers for targeted cancer agents discovered EWSR1::FLI1 was significantly associated with sensitivity to the PARP [Poly (ADP-ribose) polymerase] inhibitor (PARPi) olaparib." (PMID 36483025, 2022). "Chimeric EWS oncoproteins generated by chromosomal translocations between EWSR1 and the genes of transcription factors cause malignant tumors." (PMID 21647358, 2011). "To explore the role of the EWSR1::FLI1-dependent increase in Tau expression for cancer-associated cellular phenotypes, we engineered the EwS cell line TC-32 with inducible inhibition of Tau expression and the EwS cell line TC-71 with constitutive inhibition of Tau expression." (PMID 40319030, 2025). "Subsequent observations of variant translocations and the resulting EWSR1 fusions with different partner genes in the same tumor entity disclosed the tip of an iceberg, paving the way for discovering the phenomenon of gene promiscuity in cancer." (PMID 25478010, 2014). "The identification of specific fusion transcripts, including several variants of spicing of EWSR1 gene could help in establishing new biotechnological systems to block their aberrant activity in cancer cells." (PMID 23329308, 2013). "Chromosomal rearrangements involving FUS, EWSR1, or TAF15 drive multiple cancers, and mutations in the genes encoding the FET proteins are associated with neurodegenerative disease." (PMID 42051291, 2026). "There is a robust correlation between upregulated expression of EWSR1 and oncogenic transformations, indicating its potential role in the development of various cancers." (PMID 41472850, 2025). "It should be noted that because some clear cell myoepithelial cancers harbor EWSR1 gene rearrangements, FISH alone cannot reliably differentiate it from HCCC." (PMID 40738062, 2025). "EwS is an aggressive cancer caused by a fusion of members of the FET and ETS gene families, primarily EWSR1::FLI1." (PMID 40319030, 2025). "The patient's genetic findings, including the presence of an atypical EWSR1::FLI1 fusion and a possible cancer predisposition due to a CHEK2 variant, further complicate the clinical picture, necessitating a more nuanced treatment approach." (PMID 40630716, 2025). "Both AURKA and AURKB are known to be upregulated in many cancers and their expression has been shown to be regulated by the EWSR1/FLI1 fusion." (PMID 39518006, 2024). "The dysregulation of E2F family transcription factors is also known to promote cancer and it has been reported that in EWS, the transcription of EWSR1/FLI1 target genes is partially mediated by E2Fs." (PMID 39518006, 2024). "Additional analyses of this carcinoma have revealed positive epithelial markers via immunophenotyping and EWSR1 gene translocation through genetic testing." (PMID 39723381, 2024).